RASSF1 (Ras association domain family member 1)
Diseases named in the same sentence as RASSF1 in open-access papers (continued):
Sharing a sentence is not in itself a finding about the gene and the disease.
cancer (385 papers, 2002 to 2026). A tumor composed of atypical neoplastic, often pleomorphic cells that invade other tissues. "Ras-association domain family member 1 A (RASSF1A), a tumor suppressor gene, is usually missing in several cancers." (PMID 38840077, 2024). "Epigenetic suppression of the RASSF1‐1α promoter has been associated with poor cancer survival due to suppression of RASSF1A transcript expression." (PMID 34532864, 2021). "RASSF1 inactivation is connected with the development and progression of many cancer types, and while this inactivation can be caused by deletions and point mutations, it most often arises from methylation changes." (PMID 31450846, 2019). "Hypermethylation of RASSF1 CpG islands is associated with different types of cancer and with the risk of progression of tumorigenesis." (PMID 27725787, 2016). "A tumor suppressor gene, Ras association (RalGDS/AF-6) domain family member 1 (RASSF1) has been seen in other cancers and is believed to play a role in PCa pathogenesis." (PMID 27609145, 2016). "Epigenetic alterations of effectors of this gene, such as RASSF1 Ras association (RalGDS/AF-6) domain family member 1 (RASSF1), are very frequent in this type of cancer, although their role in tumorigenesis remains to be elucidated." (PMID 26284587, 2015). "Tumor suppressor gene, RASSF1A (Ras association domain family member 1), is involved in development or progression in the vast majority of cancers." (PMID 26112163, 2015). "The Ras association domain family 1 gene (RASSF1) was identified on chromosome 3p21.3, a region frequently deleted in cancer." (PMID 22577552, 2012). "In any case it is clear that mutations in RASSF1 in normal cells are more rare than in cancer cells." (PMID 19478941, 2009). "RASSF1 (Ras association domain-containing protein 1) is a tumor suppressor gene which plays an important role in cell cycle control, apoptosis, and cellular adhesion, and its inactivation is associated with development of many cancers." (PMID 31712935, 2020). "Since this is meant to be a screening test before more involved testing, it is important for medical personnel to simultaneously assess the risk profile of the patient to determine whether additional cancer types associated with RASSF1 should also be considered." (PMID 36648833, 2023). "We also hypothesized that higher levels of DNA methylation within LINE-1 and Alu regions and within the promoter region of the hTERT gene and that lower levels of DNA methylation within the promoter regions of the APC, BRCA1, and RASSF1 genes would be associated with a reduced risk of cancer." (PMID 29953441, 2018). "RASSF1 underexpression has been observed in several cancer types, including lung, breast, bladder, prostate, and CRC." (PMID 40004552, 2025). "By contrast, RASSF1 was methylated in an average of 38% of ccfDNA from cancer patients and only 6% of healthy patient samples." (PMID 36648833, 2023). "This involvement of epigenetic changes is supported by the reported high hypermethylation levels in genes such as APC, GTSP1 and RASSF1 in morphologically normal tissue in the prostate, that have also been shown to be good predictors of cancer development." (PMID 36131292, 2022). "The last gene whose expression was increased by radiation and melatonin was RASSF1, a tumor suppressor gene that is frequently inactivated in cancer by methylation of its promoter." (PMID 35625825, 2022). "In other reports, nitric oxide donors have been shown to induce cancer cell death by upregulating the expression of RASSF1 and CDKN1A, activating caspase 8/3 and regulating anti-apoptotic BCL-2 family members." (PMID 35205790, 2022). "For all analysed genes (p16, MGMT, and RASSF1), the methylation levels were found to be 5% higher in the cancer group compared to the control group." (PMID 31903158, 2020). "Methylation states of RASSF1 in advanced stages of cancer (stages III-IV) were higher than in early stages (stages I-II)." (PMID 31903158, 2020).
cancer (continued). "These highly methylated and lowly expressed genes, such as Ras association domain family member 1 (RASSF1A) and cyclin‐dependent kinase inhibitor 2A (CDKN2A), were predominantly enriched in multiple cancer‐associated signalling pathways." (PMID 31565863, 2019). "For example, 90% sensitivity and 86% specificity for cancer detection was determined when methylation levels of the RASSF1 A, EP300 and CALCA genes were used in combination." (PMID 31450846, 2019). "Specifically, it was demonstrated that the expression of RASSF1 in several types of cancer is reduced, because of the hypermethylation promoter." (PMID 31139559, 2019). "The Ras association domain-containing protein 1 (RASSF1), which is encoded by RAS gene altered expression, is associated with the pathogenesis of a variety of cancers." (PMID 31754358, 2019). "The comparison of tissue samples shows the increasing methylation trend from the control sample group to cancer samples in the RASSF1, CDH1 and PAX1 genes." (PMID 31450846, 2019). "Recent epidemiologic studies have reported an increased risk of cancer among individuals with higher levels of APC, BRCA1, and RASSF1 promoter methylation in tissue or in blood." (PMID 29953441, 2018). "Using bisulfite treatment followed by MS-PCR we detected methylation of the LRRC3B, APC, FHIT, and RASSF1 genes in the cfDNA of cancer patients." (PMID 27725787, 2016). "In this study, we have explored the mRNA expression of RASSF1A, MOAP-1 and the well-characterized splice variant of RASSF1, RASSF1C, in cancer cell lines and primary tumors." (PMID 27294960, 2016). "Intriguingly, methylation of the CpG island (CGI) spanning the promoter and first exon of RASSF1 has widespread prognostic value for disease-free and poor overall survival in all major sporadic cancers." (PMID 26549256, 2015). "Methylation of DAPK1 and RASSF1 genes is known to strongly contribute to carcinogenesis, metastasis and treatment failure in various types of cancer (Wong, Chang, Tang, Wei, & Kwong, 2002; Supic, Kozomara, Brankovic-Magic, Jovic, & Magic, 2009)." (PMID 27158284, 2015). "RASSF1 is a tumor suppressor gene, the inactivation of which is suggested in the development of different types of human cancer." (PMID 23226780, 2012). "Several frequently methylated loci identified in early studies, for example CDKN2A/p16, CDH13, MGMT and RASSF1 remain viable markers when assessed in a larger context, providing support for their role in cancer development/progression." (PMID 18947422, 2008). "In another study they applied a marker panel (APC, CDKN2A/p16, and RASSF1) to detect cancer in 247 patients, and reported 53% sensitivity and, in cases without a previous history of cancer, >99% specificity." (PMID 18947422, 2008). "The main pathways of methylome biomarkers were associated with calcium signalling (CACNA1E, RYR2, RYR3), cancer pathways (DCC, RASSF1, WNT1, CTNNA2), multiple neurodegenerative diseases (WNT1, DNAI1, RYR2, RYR3), immune system disorders and cell adhesion (HLA-DRA, HLA-DRB1, HLA-DRB5)." (PMID 40524349, 2025). "Conversely, in the context of anticancer therapy, these findings imply that UPR activation may be beneficial in cancers that are RASSF1‐dependent." (PMID 36723232, 2023). "Furthermore, we consider the RASSF1, we observed a higher percentage of unmethylation than methylation signals in cancer." (PMID 36329447, 2022). "Methylation of RASSF1, RASSF2, RASSF3, RASSF6, RASSF7, and RASSF9, from the RASSF regulator family was strongly associated with expression of several GMDs in a variety of cancer categories." (PMID 33676569, 2021). "RASSF1 plays an important role in the occurrence and process of malignant tumors." (PMID 35111672, 2021). "Interestingly, among the possible methylation biomarker candidates in both HPV-associated cancers, CC and HNSCC, three genes were considered by different groups: CDH1, CCNA1, and RASSF1." (PMID 34835040, 2021).
cancer (continued). "To confirm cancer-cell content in our low-volume primary tissue specimen, we have developed a multiplex epigenetic biomarker assay to detect promoter methylation of PC-associated genes including GSTP1, RASSF1, RARb and APC." (PMID 34581895, 2021). "For RASSF10, there are no reported mutations and RASSF1 mutations are below 2% across primary cancers (TCGA; analyzed)." (PMID 32047266, 2020). "In addition, we also found that RASSF1 expression correlates with SRF expression in a variety of cancers." (PMID 31414556, 2019). "Apart from SEPT9, there are other genes, such as RASSF1 (Ras association (RaIGDS7AF-6) domain family number 1) and BRCA1 (breast cancer 1), whose methylation changes could indicate malignant transformation." (PMID 31752198, 2019). "RASSF5A and RASSF1 are required to mediate the pro-apoptotic activity of MST kinases, thus it is understandable that the loss of these molecules, either due to mutations or epigenetic modifications, is strongly associated with development of cancer." (PMID 31083564, 2019). "The findings reported in this article present a new dimension to the role of RASSF1 gene in cancer." (PMID 28423657, 2017). "In addition to the tumor suppressor RASSF1, whose differential promoter hypermethylation status and expression inhibition are associated in MPNST and other cancers, we found additional regulatory genes." (PMID 28542306, 2017). "Interestingly, TUBB2C and RASSF1 are frequently silenced in human cancers and enhance apoptosis and tumor suppression." (PMID 28427156, 2017). "Many studies have demonstrated the diagnostic efficiency of DNA hypermethylation of a variety of well-known cancer-related genes, such as p16, RASSF1, APC, MGMT, DAPK, GATA5, and HOX9, in various biofluids, including bronchial aspirates, sputum, serum, plasma, and cell-free circulating DNA." (PMID 27924164, 2016). "The RASSF1 gene has several major isoforms because of alternative splicing and promoter usage, but epigenetic silencing of the longer isoform, RASSF1A, is specifically associated with cancer." (PMID 26198328, 2015). "The RASSF1 gene plays an important role in human cancer cell growth and progression." (PMID 25007054, 2014). "We chose CDKN2A and RASSF1 since hypermethylation of these genes has been widely reported in a variety of cancers including NSCLC, and the EN1 promoter region since hypermethylation of EN1 had been previously reported in a lung tumor cell line but not yet in primary NSCLC tumors." (PMID 22726460, 2012). "In addition, several of the promoter-hypermethylated genes were associated with the development of human cancers and these include GIPC2, DIRAS3, TYSPL6, EDNRB, FYN, GDNF, RASSF1, and RASSF2." (PMID 21962230, 2011). "This is the first report of high frequencies of somatic mutations in RASSF1 and RBSP3 in different cancers suggesting it may underlay the mutator phenotype of cancer." (PMID 19478941, 2009). "_ConfirmMDx® (MDxHealth, Irvine, CA, USA): this is an epigenetic assay, measuring the DNA methylation status of three genes—glutathione-S-transferase P1 (GSTP1), adenomatous polyposis coli (APC), and Ras association domain-containing protein 1 (RASSF1)—in prostate biopsy tissue without cancer." (PMID 40863429, 2025). "Furthermore, RASSF1 inactivation is one of the most common epigenetic changes in cancer." (PMID 38903861, 2024). "In contrast, the exposure of zebrafish larvae to environmentally relevant concentrations of BaP did not alter methylation of CpG island nor affected gene expression in cancer genes, including ras-association domain family member 1 (RASSF1), telomerase reverse transcriptase (tert), C-JUN, and C-MYCA." (PMID 34948252, 2021).
cancer (continued). "Up-regulated expressions of the hypo-methylated gDMs in cancer were observed for OAS2, MX2, APOL3, ABHD8, RASSF1, SIGIRR, and SPRED2." (PMID 36329447, 2022). "Similar to other carcinoma, in EC various tumor suppressor gene promotors (MLH1, PTEN, p16, APC, MGMT, RASSF1, PR and CDH1) are hypermethylated, whereas oncogene promotors (BMP, CTCFL, PARP1, CASP8) are hypo- or demethylated." (PMID 35284957, 2022). "The anti-cancer effects of miR-193a-3p are precluded by the repression of multiple target genes, including cancer related genes such as CCND1, KRAS, RASSF1, STMN1, and MCL1." (PMID 33747358, 2021). "Activating mutations of RAS and RAF, and inactivation/repression of endogenous regulators of RAS such as RASSF1 and DAB2 are common in many cancers including HCC." (PMID 32807134, 2020). "In the analysis of plasma samples from 48 NSCLC patients and 51 healthy controls, we found significant methylation profile differences between cancer and control groups at the p16, MGMT, and RASSF1 genes." (PMID 31903158, 2020). "RASSF1, one of NON-SMALL CELL LUNG tumor suppressors, play an important role in resisting the growth of NON-SMALL CELL LUNG cancer." (PMID 30792708, 2019). "TSGs such as RASSF1, CDKN2A, DAPK, APC and p14ARF are aberrantly methylated in NSCLC as well as other cancers, namely head and neck cancer (HNC), prostate cancer and cervical cancer." (PMID 34991275, 2019). "Using this system, here we show simultaneous de novo DNA methylation of genes commonly methylated in cancer, CDKN2A, RASSF1, HIC1 and PTEN in primary breast cells isolated from healthy human breast tissue." (PMID 29133799, 2017). "A recent study demonstrated that PPi hubs can be identified for a variety of cancer-related genes, including MYC, STK11, RASSF1, and CDK4." (PMID 28362357, 2017). "RASSF1A is a splicing isoform of RASSF1 and is one of the most commonly deregulated genes in cancer." (PMID 27322327, 2016). "In our study RASSF1 was also methylated in papillary RCC, but it was the only sample of this cancer subtype analysed." (PMID 27725787, 2016). "A direct correlation between RASSF1 promoter hypermethylation and reduced RASSF1A expression is observed in a variety of cancers." (PMID 23915220, 2013). "Different mutation frequencies between in vivo and in vitro experiments and in ESTs isolated from normal and cancer cells is an additional argument against the artificial nature of the hypermutation rate observed in RBSP3 and RASSF1 genes." (PMID 19478941, 2009). "Genome-wide methylation-associated biomarkers were involved in the pathways of neurodegeneration-multiple diseases (13%), cancer-related pathways (DCC, RASSF1, WNT1, CTNNA2; 13%), and Hippo, calcium signalling, cell adhesion and immune system-related pathways (all 10%)." (PMID 40524349, 2025). "Additionally, there are very significant differences between the two groups in methylation of specific genes known to be important in UM and in cancer progression in general, including PTEN, NFIA, IL12RB2, RASSF1, and HDAC4." (PMID 33092094, 2020). "Consistent with the literature 57, we noted no statistical difference in RASSF1 methylation levels between different NSCLC cancer types." (PMID 31903158, 2020). "Our results further revealed that upregulating MAPK8IP1P2 activated Hippo signaling by disrupting the repressive effect of miR-146b-3p on NF2, RASSF1, and RASSF5 expression by sponging miR-146b-3p as ceRNA, which further suppressed anoikis resistance in thryoid cancer cells." (PMID 33489905, 2020). "For the cancer group, the percentages are 25% for p16, 16.7% for MGMT, and 18.8% for RASSF1." (PMID 31903158, 2020). "Therefore, in our opinion, the ultimate goal is to identify a highly relevant methylation gene (HRMG) panel, such as RASSF1 and SFRP1, whose analysis of ctDNA would enable earlier detection of various cancers." (PMID 31752198, 2019).
cancer (continued). "For RASSF1 the previous results were strongly confirmed: Benign samples showed no methylation, whereas cancer samples present with elevated methylation." (PMID 29851970, 2018). "Moreover, our study shows that the methylation levels of selected genes, such as RASSF1 and HTATIP2, change with the cancer stages, indicating their potential values in the prognosis of ESCC." (PMID 27893424, 2017). "For example, frequent hypermethylation of CDKN2A, RASSF1, CDH13, and other genes has been observed in sputum samples from cancer-free smokers, suggesting that they may be hypermethylated early." (PMID 21577262, 2011). "RASSF1 gene mainly consists of RASSF1A and RASSF1C transcripts that are expressed on two distinct CpG promoters and present in normal human tissues; however, in many cancer, RASSF1A is inactivated and has been correlated to methylation." (PMID 19936097, 2007). "There are seven RASSF1 isoforms (A to G) generated through alternative splicing RASSF1A has been shown to reduce tumorigenicity in vivo and is frequently inactivated in a variety of primary human cancers." (PMID 17608924, 2007). "The expression of RASSF1 protein was up-regulated after challenge in the present study, which indicated that T. gondii infection might improve the resistance for NON-SMALL CELL LUNG cancer." (PMID 30792708, 2019). "Surprisingly, in carcinoma cell lines of acquired doxorubicin resistance (MCF-7_ADR, NCI/ADR-RES), methylation of CGIs from APC, HIC1 and RASSF1 was strongly reduced or completely absent." (PMID 20544021, 2010).
adenocarcinoma (20 papers, 2004 to 2026). A common cancer characterized by the presence of malignant glandular cells. "However, RASSF1 was highly significantly hypermethylated in adenocarcinoma vs. AdjNTL, and the scatterplot supports the notion that RASSF1 hypermethylation is a late event." (PMID 21731750, 2011). "RASSF1 hypermethylation approached significance but did not meet our multiple comparisons cut-off in the AIS to adenocarcinoma comparison." (PMID 21731750, 2011).
benign tumors (5 papers, 2007 to 2024). "Variable RASSF1 A methylation has also been noted in tissue samples of serous and non-serous types and benign tumours." (PMID 31450846, 2019).
infection (5 papers, 2012 to 2024). The state of being infected such as from the introduction of a foreign agent such as serum, vaccine, antigenic substance or organism. "The enforced expression of RASSF1 by a lentiviral infection resulted in the same effect." (PMID 39051186, 2024). "There were three common DE genes between cattle and sheep at the acute stage of infection: IL1RL1, CHD1 and RASSF1, and 232 common DE genes at the chronic stage of infection." (PMID 34616397, 2021). "However, q-PCR results only revealed that Rassf1 was significantly up-regulated during PmCQ2 infection, whereas Rassf6 was not significantly changed compared with the wild type." (PMID 38493147, 2024).
bacterial infection (1 paper, 2021). "The first two, MAP3K and Rassf1, are both expressed in the cytosol and are components of the Ras-Raf-MEK-ERK (MAPK/ERK) LPS-induced pathway that communicates molecular signals of a bacterial infection to drive the transcriptional changes necessary for an immune response." (PMID 33776953, 2021).
RASSF1 also shares sentences with these, for which no sentence is quoted: neuroblastoma (23 papers); nasopharyngeal carcinoma (13); small cell lung carcinoma (13); liver cancer (12); squamous cell carcinoma (12); renal cell carcinoma (10); colon cancer (9); mesothelioma (6); papillary thyroid cancer (6); Cirrhosis (5); esophageal squamous cell carcinoma (5); head and neck squamous cell carcinoma (5); parathyroid tumor (5); triple-negative breast carcinoma (5); astrocytoma (4); bladder (4); kidney tumor (4); lung squamous cell carcinoma (4); medulloblastoma (4); multiple myeloma (4); oral cancer (4); parathyroid adenomas (4); Pleural effusion (4); prostate (4); retinoblastoma (4); stomach cancer (4); uveal melanoma (4); benign breast disease (3); bladder tumors (3); CNS tumors (3).
A further 154 diseases each share a sentence with RASSF1 in 3 papers or fewer.